CCL5 (C-C motif chemokine ligand 5)
Diseases named in the same sentence as CCL5 in open-access papers (continued):
Sharing a sentence is not in itself a finding about the gene and the disease.
tumor (continued). "Tumor-infiltrating M-MDSCs produce CCR5 ligands CCL3, CCL4, and CCL5, and meanwhile, Tregs exhibit high surface expression of CCR5 and are recruited to tumor tissue by CCL4 and CCL5." (PMID 32793192, 2020). "Treatment with Romidepsin, a bicyclic class 1 selective HDAC inhibitor, has been shown to increase the expression of CCL5, CXCL9, and CXCL10 in tumor cells, promoting T cell recruitment into the tumor site and boost T cell-mediated anti-tumor function in multiple lung tumor models." (PMID 32560120, 2020). "Tumor-intrinsic upregulation of COX activity and PGE2 production may be responsible for impaired NK cell recruitment and the consequent reduction of CCL5- and XCL1-mediated intratumoral cDC1 and CTL infiltration." (PMID 32486257, 2020). "Thus, their corresponding ligands such as CCL5, CXCL9, CXCL10, and CX3CL1 effectively guide CD8+ CTL mobilization from regional lymph nodes to tumor tissues." (PMID 31991604, 2020). "Intriguingly, this technology is based on CCL5, a chemokine produced by MSCs upon contact with tumor cells, which allows the activation of the CCL5 promoter driving HSV-TK genes only in tumor-infiltrating MSCs, restricting expression of the prodrug-converting enzyme to the tumor microenvironment." (PMID 33117154, 2020). "Lastly, after the purified tumour-infiltrating PMN-MDSCs were cultured for 24 h in vitro, cells from the HSD group expressed more TNF-α and ICAM-1 and less prostaglandin E2 (PGE2), Arg1, CCL2 and CCL5 than those from the NSD group." (PMID 32265505, 2020). "Scarcity of CCL5 secreted by hematopoietic precursors, rather than that from peripheral tissues or tumor cells, reduces primary tumor growth and metastatic disease in mice." (PMID 32630699, 2020). "In addition, the receptors CCR2 and CCR5 were increased in pre-metastatic lung samples, which was probably due to expression on tumor-infiltrated neutrophils, and lung cancer cells were found to secrete their ligands CCL2 and CCL5." (PMID 33105656, 2020). "For example, MSCs cocultured with breast cancer cells overexpressed CCL5, which stimulates tumor cell motivation and metastasis, whereas this effect was not evident in MSCs separated from tumor cells with a permeable membrane." (PMID 32793565, 2020). "We hypothesize that the ASCs at the TNBC tumor boundary bind to MDA-MB-231 cells, generating high levels of CCL5." (PMID 32252260, 2020). "This review focuses on the CCL5/CCR5 axis, which is the main actor in tumor progression." (PMID 32630699, 2020). "EVs derived from DCs exposed to hyperthermia and stress contain increased amounts of heat shock proteins and chemokines (CCL2, CCL5, and CCL20) and as such, promote infiltration of tumor-attacking T cells and DCs into the tumor microenvironment of mice treated with these EVs." (PMID 32765528, 2020). "As shown in our studies, the varying levels of CCR5 expression in the presence and absence of CCL5 determined the role of the CCR5/CCL5 axis in promoting tumor growth and progression; this was supported by the tissue microarray data." (PMID 32260550, 2020). "In addition, tumor-infiltrating CD8+ T cells of the mice treated with anti-PD-L1 and/or anti-CCL5 antibodies exhibited enhanced IFN-γ production relative to the control isotype mice, especially in the combination treatment group." (PMID 32300119, 2020). "In this context, CCL5 plays a fundamental role in TME building and tumor growth." (PMID 32630699, 2020). "However, as other cytokines, not necessarily a product of inflammasome activity, are left unchecked by IL-1β or CCL5 inhibition, MDSC recruitment and tumor metastasis would be unaffected in the long run." (PMID 31685946, 2020). "In the advanced malignant tumor, chemokines such as CCL5 and CCL18 could enhance adhesion and mobility of cancer cells to accelerate tumor invasion and metastasis." (PMID 32134471, 2020).
tumor (continued). "Collectively, these results indicate that GBE1 blockade induces IFN-I production via STING signaling pathway, accompanied by upregulation of PD-L1 in LUAD cells, which further enhances the secretion of CCL5 and CXCL10 to recruit CD8+ T lymphocytes in the tumor microenvironment." (PMID 31221150, 2019). "Collectively, GBE1 prevents CCL5 and CXCL10 secretion in LUAD cells, which may further affect the recruitment of T lymphocytes into the tumor microenvironment." (PMID 31221150, 2019). "A notable observation in our study is that while CCL5 expression promoted recurrence, knockout of CCL5 in tumor cells did not delay recurrence." (PMID 30990165, 2019). "Macrophages may differentiate from cells in the tumor microenvironment or be recruited via CCL2, CCL5, and CXCL12." (PMID 30931508, 2019). "Additionally, irradiation enhanced the homing of the antigen-specific T cells to tumor tissues via the increased release of CCL5, CXCL9, and CXCL11 from tumor cells." (PMID 31921127, 2019). "Our study leverages data from plasma RNA and CTCs, published studies and focused data mining, to propose a testable model in which high concentration of PF4 induces platelet attraction into the tumor microenvironment and regulates expression and/or availability of CLU, CCL5, TGFB1, SRGN and SPARC." (PMID 31215484, 2019). "Tumor regression in response to combination treatments correlated strongly with elevated tumor expression of CD8b, Ifng, Tnfa, Ccl5 and Il18 in the non-injected tumors." (PMID 31921384, 2019). "CXCL8 and CCL5, produced by bone marrow- and adipose-derived MSCs were prime inducers of metastasis in TNBC, acting by elevating the proliferation and invasive properties of the tumor cells, and their resistance to chemotherapy." (PMID 31031757, 2019). "Acid-induced NF-κB activation downstream promotes the secretion of several cytokines, chemokines, and growth factors (IL1a, IL1b, IL6, IL8, IL23a, CCL5, CCL7, CXCL2, GM-CSF, and G-CSF) that can elicit local cancer aggressiveness, tumor immune escape, and tumor-induced nociception and hyperalgesia." (PMID 30825056, 2019). "The splenic eosinophils in cryo-thermal-treated mice expressed high level of chemokines and pro-inflammatory cytokines (CCL5, CXCL10, IFN-γ, IL-6, IL-12 and IL-15), which could create immunostimulatory microenvironment contributing to anti-tumour immunity." (PMID 31519961, 2019). "NK cells play a critical role in anti-tumor immunity and they could respond to several chemokine signals, including CCL3/CCL4/CCL5 via CCR5 and CXCL9/CXCL10 via CXCR340–42." (PMID 30718511, 2019). "Both CCL5 and TGF-β can alter the immune context by blocking CD8+ T-cell activity and stimulating the T-reg subpopulation with the generation of an immune suppressive phenotype in the tumor microenvironment." (PMID 31500143, 2019). "Additionally, hypoxia can also promote TAMs to infiltrate in the inner region of the tumor by secreting chemokines such as chemokine C-C motif ligand 2 (CCL2), CCL5 and CSF-1." (PMID 31629410, 2019). "Tumor-derived fibroblasts produce MCP-1 (CCL2) and RANTES (CCL5) could attract Th17 cells intensively." (PMID 31024835, 2019). "Non-remissive and later stage BrCa was reported to be correlated with CCL5 expression, possibly due to its ability to promote pro-invasive factor MMP9 and monocyte migration to the BrCa tumor site, in which they undergo polarization allowing them to support tumor progression through angiogenesis." (PMID 30850664, 2019). "Although in the current study we find that in residual tumors CCR5 is expressed at higher levels in macrophages than on tumor cells, it is possible that tumor cell-expressed CCR5 may mediate at least some of the effects of CCL5 on tumor recurrence." (PMID 30990165, 2019). "Taken together, these results suggest that CCL5 expression is sufficient to accelerate recurrence, but tumor-derived CCL5 is not necessary for recurrence following Her2 downregulation." (PMID 30990165, 2019).
tumor (continued). "This impaired anti-tumor ability might be attributable to the decreased accumulation of iNKT cells in the lungs and damage to their production of critical anti-tumor factors (IFN-γ and CCL5) after α-GalCer administration (days 0 and 4) 50,51." (PMID 30250136, 2018). "KLRC1 and CCL5 have been shown to be involved in compromising anti-tumoral responses with KLRC1 inhibiting the killing ability of CD8+ T cells and CCL5 recruiting immunosuppressive T regulatory cells into the tumor microenvironment." (PMID 30151353, 2018). "This indicated that in the iLID3W mice, in contrast to controls, tumor associated neutrophils (TAN) did not lose the expression of markers characteristic of the pro-inflammatory (N1) phenotype (high ICAM-1 and low CCL5 and VEGF expression)." (PMID 29644002, 2018). "Moreover, CCR5 is recruited at the immune synapse formed between T cells and tumor target cells upon interaction of CD103 with E-cadherin, promoting retention of TRM cells at the tumor site by inhibiting their sensitivity to a CCL5 chemotactic gradient." (PMID 30158938, 2018). "Based on the data that both host-derived CCL5 and tumor cell-derived CCL5 play important role on tumor progression in CRC, we chose KO + CT26shCCL5 (CCL5−/−) mice and the control group WT + CT26shNTC (CCL5+/+) to explore the role of CCL5 in CRC in the following studies." (PMID 29991744, 2018). "As expected, adoptive transfer of CCL5+/+ CD8+ T cells did not enhance tumor growth and metastasis of CCL5−/− mice and vice versa that CCL5−/− CD8+ T cell did not change the phenotype of CCL5+/+ mice." (PMID 29991744, 2018). "CCL5 may act indirectly by recruiting the TME, monocytes/macrophages, or fibroblasts that, in turn, may promote and sustain tumor cell survival/proliferation." (PMID 29772686, 2018). "In immunodeficient mice coinjected with KATO III and PBMCs, neutralization of CCL5 decreased tumor growth, suggesting that GC cells may induce CD4+ T cells to secrete the tumor-promoting CCL5 and may inhibit the anticancer activity of CD8+ cells." (PMID 29772686, 2018). "Tumor-derived soluble mediators such as chemokines (CCL2, CCL5, CXCL12), colony-stimulating factor-1 (CSF-1), TGF-β, IL-10, prostaglandin E2 (PGE2) and metabolites (lactate) likely contribute to the development of TAMs with M2-like phenotype and tumor-promoting properties." (PMID 30563569, 2018). "High levels of CCL5 protein in lysates from Ptgs1/Ptgs2−/− BRAFV600E tumors but not control BRAFV600E tumor lysates were confirmed by cytometric bead array (CBA) analysis." (PMID 29429633, 2018). "TAMs have been shown to promote tumour invasion, growth, angiogenesis, metastasis, and immunosuppression by releasing pro-tumour mediators such as MMPs, VEGF, and various chemokines such as CCL5 (RANTES)." (PMID 29342940, 2018). "Other cells such as CD8+ T cells and innate lymphocytes [e.g., γδ T cells, innate lymphoid cells (ILC1s)] are in principle able to produce both CCL5 and XCL1 and might contribute to cDC1 recruitment under certain circumstances or in other tumor contexts." (PMID 30352680, 2018). "However, when the tumor cells were also stimulated with the type 1 cytokine IFNγ and TNFα an increased expression of CCL2, CCL5, CXCL9, CXCL10 and IL-6 was detected when compared to treatment with the control antibody." (PMID 30192802, 2018). "High expression of the CCL5 and CXCL12 genes in Lauren’s diffuse type of GC and increased expression of ADAMTS1, CXCL12, and CCL19 genes were found in peritoneal metastasis, suggesting their involvement in tumor progression." (PMID 29772686, 2018). "Conversely, the lower Ccl5 to Ccl7 and Ccl5 to Ccl2 expression ratios in F5-T1 support a TME containing less T-lymphocyte chemoattractants and with a greater inflammatory reaction, also attested by the maximal fibrinogen content that characterized this tumor." (PMID 29662647, 2018).
tumor (continued). "Multiple Th1 cytokines and downstream targets were overexpressed in hot tumours (IFNG, CCL4, CCL5, CXCL9, CXCL10), along with costimulatory and coinhibitory receptors, suggesting these tumours were marked by a state of lymphocyte activation and counter-responses thereto." (PMID 30104673, 2018). "A recent analysis of 20 different cytokines and chemokines (some also included here) in culture supernatants harvested from HNSCC tumor tissue-derived cell suspensions, showed, in accordance with the present study, high tumor related levels of CXCL9, CXCL10, and CCL20 and decreased levels of CCL5." (PMID 29587383, 2018). "On this note, it seems intuitive to preferentially target the XCL1/XCL2-XCR1 axis rather than CCL5 to guide cDC1 into tumors, thereby ensuring that CCL5-mediated recruitment of tumor-promoting immune cells such as macrophages or regulatory T cells is avoided." (PMID 29429633, 2018). "Indeed, chemokines such as CCL3, CCL4, CCL5 and CXCL10 were significantly increased in tumours injected with MV-Edm." (PMID 28701757, 2017). "Numerous cell types influence macrophage function including the tumor cells themselves, which not only recruit macrophages to both primary and metastatic tumor sites by secreting chemokines such as CCL2, CCL5 and CXCL12, but also differentiate and polarize them to a tumor-promoting phenotype." (PMID 28881599, 2017). "The increased macrophage recruitment may be a response to the increased chemokine release by tumor cells such as CXCL-10, CCL-2, CCL3, CCL4, and CCL5." (PMID 28670313, 2017). "Exosomes derived from heat-stressed tumor cells (HS-TEX) which contain chemokines, such as CCL2, CCL3, CCL4, CCL5, and CCL20, could chemoattract and activate dendritic cells (DC) and T cells more potently." (PMID 29164149, 2017). "Whereas in the absence of OV infection enhanced tumour production of CCL-5 resulted in Treg recruitment and progression, vvCCL-5 infection led to CD4+ effector T-cell infiltration and a Th2 skewed immune response." (PMID 29157300, 2017). "The expressions of CCL5 and TGF-β1 at tumor margin were also higher than those at tumor center." (PMID 29299159, 2017). "Furthermore, Tumor Necrosis Factor Alfa (TNF-α) activates MSCs to secrete chemokine (C-C motif) ligand 5 (CCL5), C-C chemokine receptor type 2 (CCR2), and the interleukin 8 receptor, beta (CXCR2) ligands that in turn recruit CXCR2+ neutrophils into the tumor." (PMID 28473858, 2017). "CCL5 recruits the tumor cells to the LN and lungs; VEGF helps build blood vessels in the LN to facilitate tumor cell survival; VEGF produced in the lung helps the tumor cells to extravasate into the lung." (PMID 28947965, 2017). "In our experiments, compared to EL4-Axl cells, the tumor tissues of EL4-Axl-tumor bearing mice demonstrated high mRNA expression of CCL5 and CCR5 (data not shown)." (PMID 28423548, 2017). "In addition, western blotting revealed that CCL5 and CXCL12 protein levels were significantly higher in the brain tissues of mice that developed tumours after ESC or iPSC transplantation (P < 0.05)." (PMID 27417157, 2016). "Furthermore, downregulation of miR-214 has also been demonstrated to directly influence chemokine (C-C motif) ligand 5 CCL5 production, whose increased levels lead to enhanced tumor growth, by stimulating OvCa cells invasion." (PMID 27349385, 2016). "In addition, downregulation of SK1 in B16 led to an increased expression of Th1 cytokines (IL-12, TNFa, IFNg) and chemokines (CCL5, CXCL9, CXCL10) into the tumor." (PMID 27708249, 2016). "CCL5 (RANTES) is a chemokine that exerts an important role in inflammation, by orchestrating the migration of monocytes and T cells to injured, infected and tumour sites." (PMID 27335323, 2016). "The expression of Ccr5 and its ligands, Ccl3 and Ccl4, but not Ccl5, were markedly increased in tumor sites 7 days after the injection." (PMID 27340784, 2016).
tumor (continued). "These cells were shown to secrete proinflammatory cytokines and chemokines such as IL-6, CCL5, and CXCL3, which could in turn serve to further recruit additional proinflammatory cells to the tumor margins." (PMID 26884646, 2016). "Regarding the mechanisms involved in the increased recruitment of macrophages into ARF−/− tumor xenografts, upregulation of chemokines and growth factors including CCL-17, CCL-22, CCL-5 and TGF-β might be critical." (PMID 27572316, 2016). "Furthermore, CCL5 and CXCL12 levels in the brain tissues of mice with grade 3 tumours were higher than in those with grade 2 and 1 tumours." (PMID 27417157, 2016). "Additionally, we found that IR treatment induces an influx of CD8+ T cells into the tumor accompanied by elevated expression of CXCL10 and CCL5 in the tumor, both of which are among the signature genes highly expressed in “T cell-inflamed” tumors." (PMID 27343548, 2016). "At the same tumour grade, there were no obvious differences in CCL5 and CXCL12 levels between the ESC and iPSC groups." (PMID 27417157, 2016). "It is intriguing to speculate that our studies with CCL5 and CCR5 may have broader implications for other chemokine/chemokine receptor interactions purported to be important in neoplasias." (PMID 27335323, 2016). "Analysis of the tumor tissues revealed that radiation up-regulates both CCL2 and CCL5." (PMID 27014915, 2016). "This work demonstrates that although the chemokine crosstalk in the tumor microenvironment (TME) is a complex and overall poorly understood process, both the CCL2:CCR2 and CCL5:CCR5 ligand/receptor pairs have been identified as likely therapeutic targets across several types of cancers." (PMID 27852031, 2016). "No statistically significant main effects of tumor or interactions with time were evident for other inflammation-related genes (Il-6, Ccl5, Ccl1, Ccl22, Cx3cl1; p>0.05)." (PMID 27548621, 2016). "In conclusion, specific therapies inhibiting CCL5/CCR5 may not only prevent malignant progression, but also significantly delay tumor growth by inhibiting the angiogenic switch in primary tumors and disseminated micrometastases." (PMID 27863423, 2016). "For example, CCL5 when expressed from an oncolytic VacV, was able to increase tumor infiltration of DCs and CD4+ but not CD8+ T-cells." (PMID 28536388, 2016). "Grade 3 tumours expressed Ccl5 at levels that were 3-, 31- and 78-fold higher compared with grade 2, 1 tumours and no tumour, respectively, in the ESC and iPSC groups." (PMID 27417157, 2016). "Surprisingly, other than CCL5, all key factors and immune-related functions were not active in spleens from non-tumor bearing old mice." (PMID 26497558, 2015). "Peritoneal lavages and lysates of recovered tumor were monitored for CCL2, CCL9 and CCL5 levels." (PMID 26647964, 2015). "Likewise, in an experimental melanoma model, tumor-infiltrating Tregs expressed CCR5 and preferentially migrated toward its ligands CCL3, CCL4, and CCL5, which were elaborated by tumor-infiltrating myeloid-derived suppressor cells (MDSCs)." (PMID 26217588, 2015). "Tumor-promoting macrophages are recruited from blood to tumor sites by CCL2 and CCL5." (PMID 25909600, 2015). "These analyses revealed that the tumours are characterized by expression of inflammatory chemokines (CCL2, CCL5, CCL7, CCL8, CCL12, CXCL9, CXCL10 and CX3CL1), reflected by an enrichment of activated Foxp3− and Foxp3+ T cells expressing T helper type 1-associated chemokine receptors." (PMID 25495686, 2015). "Mechanically, TAMs are generally recruited from blood monocytes by diverse chemokines such as CCL2 (MCP-1), CCL5, CCL7, CXCL8 and CXCL12, migrate to diverse areas of the tumor microenvironment and differentiate according to surrounding cellular or environmental stimuli." (PMID 25685069, 2015).